TRPV4 (transient receptor potential cation channel subfamily V member 4)
Diseases named in the same sentence as TRPV4 in open-access papers (continued):
Sharing a sentence is not in itself a finding about the gene and the disease.
hematoma (1 paper, 2018). A hematoma is a collection of blood from a vascular structure into an extravascular space. "Immunofluorescence staining also revealed increased TRPV4 expression around the hematoma 24 h after ICH compared with the sham group (p < 0.05)." (PMID 29636662, 2018). "First in addition to hematoma-induced mechanical stress, cell-swelling-induced osmotic alterations and metabolites of AA released in response to membrane phospholipid degradation may also contribute to TRPV4 activation after ICH; thus, further studies should be performed to clarify these issues." (PMID 29636662, 2018).
Hepatic steatosis (1 paper, 2024). Steatosis is a term used to denote lipid accumulation within hepatocytes. "TRP channels exhibit both pro- and anti-hepatic steatosis activity, evidenced by the observation that loss of TRPC5, TRPV1, and TRPM2 protected, whereas loss of TRPV4 aggravated hepatic steatosis." (PMID 39871879, 2024).
hepatoblastoma (1 paper, 2024). Hepatoblastoma (HB) is a malignant hepatic tumor and is the most common pediatric liver cancer. "Evidence from previous studies confirmed that TRPV4 channels regulate Ca2+ influx and release in human hepatoblastoma cells; meanwhile, the hepatocyte growth factor/scatter factor activates TRPV4 and TRPV1 channels, gradually amplifying the signaling and leading to cell mortality." (PMID 38730655, 2024).
Hyperinsulinemia (1 paper, 2025). An increased concentration of insulin in the blood. "The findings of this study suggest that TRPV4 may be one of the mechanoreceptors potentiated by hyperinsulinemia in T2DM and such an augmentation of channel currents may induce abnormal EPR activity in T2DM." (PMID 40343778, 2025).
Hyperkeratosis (1 paper, 2022). Hyperkeratosis is a histopathological term defining a thickened stratum corneum and may be present in many different skin conditions, with many possible overlaps. "This may lead to a hypotonic activation of TRPV4 calcium channels and an increase in concentration of intracellular calcium, which may cause keratinocyte apoptosis to increase, and as a result, hyperkeratosis." (PMID 36076978, 2022).
inflammatory skin disease (1 paper, 2023). Inflammatory skin disorders covers a broad category that includes many conditions ranging in severity, from mild itching to grave medical health complications These disorders are common in people of all ages and races. "Having clarified that TRPV4 activation suppresses inflammatory responses in human macrophages and monocytes, we next investigated the relationship between TRPV4 expression and macrophage polarization markers in inflammatory skin diseases." (PMID 36645854, 2023).
intervertebral disc degeneration (1 paper, 2023). "Current evidence suggests that Piezo1 channels are implicated in the pathogenesis of intervertebral disc degeneration, while transient receptor potential vanilloid type 4 (TRPV4) also contributes to this process." (PMID 38068915, 2023). "The low osmotic pressure environment facilitates the upregulation of TRPV4 ion channels, leading to an augmented secretion of pro-inflammatory cytokines and thereby establishing a detrimental cycle of intervertebral disc degeneration." (PMID 38068915, 2023). "Additionally, Piezo 1, transient receptor potential vanilloid type 4 (TRPV4), tension response enhancer binding protein (TonEBP), potassium ions, zinc ions, and tungsten all play a role in the process of intervertebral disc degeneration." (PMID 38068915, 2023).
kidney damage (1 paper, 2022). "TA might be involved in kidney damage, causing TRPV4 dysfunction by decreasing the expression of MAP7D1." (PMID 35477741, 2022).
leiomyosarcoma (1 paper, 2025). An uncommon, aggressive malignant smooth muscle neoplasm, usually occurring in post-menopausal women. "In addition, a recent study revealed that TRPV4 may significantly promote the progression of leiomyosarcoma." (PMID 40919118, 2025).
Lewis Lung Carcinoma (1 paper, 2019). "This, in turn, resulted in excessive tumor growth and vascularization in a mouse model deficient of TRPV4 and subcutaneously injected with Lewis Lung Carcinoma (LLC) cells." (PMID 32038296, 2019).
limb ischemia (1 paper, 2020). A ischemia that involves the limb. "This supports the important role of TRPV4 in promoting adaptation to acute limb ischemia." (PMID 32103073, 2020).
liver cirrhosis (1 paper, 2017). "TRPV4 promotes HSC proliferation, therefore the authors concluded that miR-203 is a liver cirrhosis inhibitor." (PMID 28355233, 2017).
melanocytic nevus (1 paper, 2024). A neoplasm composed of melanocytes that usually appears as a dark spot on the skin. "We compared TRPV4 expression in sweat glands from patients with melanocytic nevus (n = 10, ages; 15–63) as controls and patients with AIGA (n = 10, ages; 24–55) using a commercially available anti-TRPV4 antibody different from the one utilized in the mouse samples." (PMID 38963781, 2024).
memory impairment (1 paper, 2025). "Based on these findings, TRPV4 hyperactivity played an essential role in age-related memory impairment in normal-aged female rats." (PMID 41341920, 2025). "However, the involvement of TRPV4 activity in age-related memory impairment remains unknown." (PMID 41341920, 2025).
muscular disease (1 paper, 2022). Myopathy is a peripheral nervous system disease consisting of any abnormal condition or disease of the muscular tissues; commonly designates a disorder involving skeletal muscle. "A mutation in TRPV4 was found near the PACSIN3‐binding site, suggesting that lack of an interaction with PACSIN3 may be involved in the development of certain forms of TRPV4‐associated muscular diseases." (PMID 34990060, 2022).
myopia (1 paper, 2024). "It is also worth noting that our study describes cases of HM in individuals with variants in genes that have not yet been clearly associated with the development of myopia (TRPV4, TUBA1A, SBDS, KIDINS220)." (PMID 39495751, 2024). "In one (1/18) child, we found genetic variants defined as VUS, and in four (4/18) children, we found (likely) pathogenic variants in the genes TRPV4, TUBA1A, SBDS, KIDINS220, which have not been previously associated with the development of myopia." (PMID 39495751, 2024).
Myotonia (1 paper, 2021). An involuntary and painless delay in the relaxation of skeletal muscle following contraction or electrical stimulation. "Besides peripheral neuropathies, a very recent study elegantly showed that skeletal muscle TRPV4 channels are involved in mechanically induced myotonia because the latter is inhibited by TRPV4 inhibitors or missing in muscles of TRPV4−/− mice." (PMID 34208776, 2021).
non-alcoholic steatohepatitis (1 paper, 2020). "Contrary to our current findings, TRPV4 was found to attenuate oxidative stress-mediated M1 macrophage polarization spectrum in an experimental model of non-alcoholic steatohepatitis liver." (PMID 33381111, 2020).
non-small cell lung carcinoma (1 paper, 2025). A group of at least three distinct histological types of lung cancer, including non-small cell squamous cell carcinoma, adenocarcinoma, and large cell carcinoma. "TRPV3 promotes angiogenesis in non-small-cell lung cancer (NSCLC) through the HIF-1α/VEGF pathway, while TRPV4 modulates mechanosensitivity in tumor endothelial cells to regulate vascular maturation." (PMID 41155636, 2025).
overactive bladder syndrome (1 paper, 2017). "Loss-of-function of this mechanism in genetic models such as Trpv4−/− mice or after pharmacological block of TRPV4 channels or SK3 channels leads to enhanced transient contractions and symptoms experienced in overactive bladder syndrome." (PMID 28947806, 2017).
overnutrition (1 paper, 2023). An imbalanced nutritional status resulting from excessive intake of nutrients. "Our results and data from TRPV4 and Piezo1 mouse models support the overarching notion that adipocyte mechano-signaling regulates systemic metabolism, especially under conditions of overnutrition." (PMID 36749637, 2023).
pneumococcal infection (1 paper, 2021). Infections with bacteria of the species streptococcus pneumoniae. "In TRPV KO mice (especially TRPV4 KO), bacterial dissemination was observed in multiple organs 3 days after pneumococcal infection, although it was unlikely among wild type." (PMID 34804016, 2021). "In conclusion, both TRPV1 and TRPV4 channels regulated the development of pneumococcal infections arising from nasal colonization in an adult mouse model." (PMID 34804016, 2021). "In this report, we demonstrated for the first time that TRPV1 and TRPV4 were involved in the development of invasive pneumococcal infections after establishment of nasal colonization by using knockout mouse strains." (PMID 34804016, 2021).
pneumococcal pneumonia (1 paper, 2021). A febrile disease caused by STREPTOCOCCUS PNEUMONIAE. "TRPV1 and TRPV4 channels are suggested to contribute to the suppression of pneumococcal pneumonia in the coinfection model." (PMID 34804016, 2021). "The TRPV4 channel in particular may play an important role in the prevention of secondary pneumococcal pneumonia and its subsequent development of lethal infection during influenza virus infection." (PMID 34804016, 2021).
polycystic liver diseases (1 paper, 2011). "Taken together, the experimental findings related to TRPV4 function in the digestive system attribute this TRP channel a pathophysiological role in inflammation, pain, hyperalgesia and polycystic liver disease." (PMID 21420431, 2011).
polyneuropathy (1 paper, 2022). A disease or disorder affecting more than one nerve. "Hereditary polyneuropathy with early-onset axonal neuropathy with vocal cord involvement was suspected and targeted Sanger sequencing of TRPV4 in blood DNA revealed the exon 12 variant c.1856T>C (NM_021625.5) leading to p.(Leu619Pro) in the proband, but absent in both parents." (PMID 33685999, 2022).
presbyopia (1 paper, 2021). The normal decreasing elasticity of the crystalline lens that leads to loss of accommodation. "Our results suggest that G-Hsd treatment affected TRPV4 localization to control the Na+/K+ ATPase pump, maintain lens intracellular osmolarity, and prevent lens hardening and presbyopia." (PMID 33673261, 2021).
Renal cyst (1 paper, 2023). A fluid filled sac in the kidney. "We show that high KCl diet increases renal TRPV4 levels, augments TRPV4‐dependent Ca2+ influx in freshly isolated cystic cell monolayers and markedly slow the development and growth of renal cysts in PCK453 rats." (PMID 36946001, 2023).
Seizure (1 paper, 2023). A seizure is an intermittent abnormality of nervous system physiology characterized by a transient occurrence of signs and/or symptoms due to abnormal excessive or synchronous neuronal activity in the brain. "Next, to better understand the mechanisms that cell-specific NFIA upregulation controls astrocyte reactivity in 4-AP-induced seizure model, we test the effect of NFIA knockdown on the expression of TRPV4 and its functional activity in primary cultured astrocytes." (PMID 37880726, 2023).
severe acute respiratory syndrome (1 paper, 2020). A viral respiratory infection caused by the SARS coronavirus. "The transient receptor potential channel subfamily V member 4 (TRPV4) channel has recently emerged as a pharmacological target for several respiratory diseases, including the severe acute respiratory syndrome coronavirus 2 (SARS-CoV-2) infection." (PMID 33081023, 2020).
Sjögren’s syndrome (1 paper, 2024). "Problems with exocrine gland function in patients with Sjögren’s syndrome as well as the low TRPV4 expression levels in patients with AIGA suggest that TRPV4 could be a key molecule involved in these diseases and that novel treatment strategies could target TRPV4 and/or ANO1." (PMID 38963781, 2024).
Thiemann disease (1 paper, 2019). "We describe a father and son referred with a diagnosis of Thiemann disease who were subsequently identified with a heterozygous variant (c.809G > T) in TRPV4." (PMID 31248428, 2019). "Here, we describe a father and son referred with a diagnosis of Thiemann disease whom were subsequently identified with a pathogenic TRPV4 variant." (PMID 31248428, 2019). "TRPV4 variants cause FDAB while the familial nature of Thiemann disease is consistent with a genetic etiology." (PMID 31248428, 2019). "Our report describing a TRPV4 variant in a father and son referred with a diagnosis of Thiemann disease suggests the historical accounts of these two different phenotypes may be inaccurate in some instances, and that they may be different manifestations of the same disease." (PMID 31248428, 2019).
tongue cancer (1 paper, 2025). A malignant neoplasm affecting the tongue. "We also examined the effect of TRPV4 inhibition on orofacial mechanical nociception measured with von Frey filaments in the tongue cancer model." (PMID 40144515, 2025). "TRPV4 inhibition also decreased facial nociception in tongue cancer mice." (PMID 40144515, 2025). "Immunohistochemical analysis of TRPV4 expression in mice bearing tongue cancer xenografts or allografts revealed TRPV4 immunoreactivity (ir) on the cell membranes of the tongue epithelium, ducts of the von Ebner glands and blood vessels, as well as mouse cancer cells." (PMID 40144515, 2025). "While we have previously reported increased expression of TRPV1 and TRPA1 in TGs of mice with tongue cancer, we find that TRPV4 was neither abundantly expressed in nerves innervating murine tongue cancer nor in the TGs of mice with tongue cancer." (PMID 40144515, 2025). "Membranous TRPV4-ir was also not detected in trigeminal ganglia (TG) from the tongue cancer mice." (PMID 40144515, 2025).
trigeminal neuralgia (1 paper, 2021). Trigeminal neuralgia is a nerve disorder that causes a stabbing or electric-shock-like pain in parts of the face. "Our objective of this study is to determine the molecular mechanism of MAPKs (mitogen activated protein kinase systems) on TRPV4 (transient receptor potential vanilloid 4)-mediated trigeminal neuralgia (TN)." (PMID 34499186, 2021). "The primary objective of this study is to elucidate the major molecular mechanism of MAPK pathway on TRPV4-mediated trigeminal neuralgia." (PMID 34499186, 2021). "We found that down-regulation of MAPK pathway could alleviate TRPV4-mediated trigeminal neuralgia, via inhibiting the activation of histone acetylation." (PMID 34499186, 2021).
Ventricular arrhythmia (1 paper, 2021). "Following I/R, TRPV4 led to membrane potential depolarization, slower action potential kinetics, and increased incidence of ventricular arrhythmia." (PMID 34867442, 2021).
viral pneumonia (1 paper, 2022). Inflammation of the lung parenchyma that is caused by a viral infection. "Nevertheless, our data suggest that TRPV4 inhibitors may represent an attractive therapy for viral pneumonia as they may both suppress viral load via DDX3X signaling and dampen the associated inflammatory response via the S100A7/RAGE pathway." (PMID 35396513, 2022).
cancer (97 papers, 2007 to 2025). A tumor composed of atypical neoplastic, often pleomorphic cells that invade other tissues. "The complexity of TRPV4 extends beyond its expression patterns, with the channel actively participating in the regulation of cellular functioning, which is associated with cancer progression." (PMID 38730655, 2024). "The development of TRPV4 inhibitor will be of great importance in overcoming treatment failure caused by cancer metastasis." (PMID 37369706, 2023). "Intriguingly, we demonstrated that several cancer-related mutations of RhoA also disrupt the TRPV4-RhoA binding interface." (PMID 37353484, 2023). "Studies increasingly show that the aberrant expression of TRPV4 in tumor tissues is associated with cancer progression." (PMID 36619170, 2022). "We found that TRPV4 expression was positively correlated with the infiltration level of TAMs and tumor associated fibroblasts (CAFs) in pan-cancer using the TIMER2 database." (PMID 34262942, 2021). "To explore the indicator function of TRPV4 in anti-cancer drug selection, we analyzed the association between TRPV4 expression and IC50 values of anti-cancer drugs using data from the GDSC database." (PMID 34262942, 2021). "Cumulative evidence has implicated that abnormal expression of the TRPV4 channel contributed to human cancer progression." (PMID 34814869, 2021). "Transient receptor potential vanilloid 4 (TRPV4) is a calcium-permeable cation channel that has been associated with several types of cancer." (PMID 33230171, 2020). "This is consistent with our previous data that implicated a mechanical role of TRPV4 overexpression in metastasis by promoting cancer cell softness and migration." (PMID 28530703, 2017). "Modulating TRPV-4 activity in cancers that overexpress it not only inhibits cell proliferation but also enhances the efficacy of chemotherapy and radiotherapy while reducing cancer-associated pain." (PMID 40109334, 2025). "TRPV4 has also been associated with angiogenetic process through the regulation of Rho kinase pathway in endothelial cells and may thus promote cancer cell spread through the induction of tumor vasculature." (PMID 38514727, 2024). "Since the rapid proliferation of cancer cells severely squeezes the bone marrow cavity, which causes changes in cell surface pressure, and TRPV4 could sense changes in cell surface mechanical and osmotic pressure, we chose to study TRPV4 in the TRPV family." (PMID 37190609, 2023). "However, deficiency of TRPV4 causes reduced vascular E-cadherin level and destabilizes tumor vessel integrity, leading to cancer cells lung metastasis." (PMID 36046433, 2021). "Additionally, TRPV4 has been linked to cell proliferation through the CaMKII pathway and regulation of apoptosis in distinct cancer models." (PMID 34356643, 2021). "Increasing studies associate TRPV4 with multiple processes of cancer." (PMID 32843668, 2020). "Taken together, TRPV4 overexpression is associated with poorer survival rate and cancer aggression." (PMID 28530703, 2017). "Since AKT and FAK signaling pathways are commonly associated with cell motility, we hypothesized that TRPV4’s function in cancer cell migration involve AKT and/or FAK-mediated signaling pathways." (PMID 28530703, 2017). "Thus the underlying mechanisms by which TRPV4 regulates cancer cell growth remain to be elucidated." (PMID 31189890, 2019). "Multiple Ca2+-handling proteins, including CACNA1D, CACNA2D1, TRPV4, TRPV1, TRPM4, MCU, and RyR1, exhibit cancer-associated overexpression or functional changes, correlating with poor prognosis and aggressive disease features." (PMID 41226294, 2025). "We also analyzed the differential expression of Sox4, E2f1, Trpv4 and Trim6, which are the genes important for cancer stem cell behavior and function." (PMID 40568073, 2025). "Silencing the TRPV4 gene impaired the ability of cancer cells to respond to mechanical cues, leading to less calcium depletion, smaller volume changes, and reduced mobility." (PMID 40256982, 2025).